NRN1 (neuritin 1)
Diseases named in the same sentence as NRN1 in open-access papers (continued):
Sharing a sentence is not in itself a finding about the gene and the disease.
tumor (10 papers, 2017 to 2025). "Given its multifaceted influence on tumor progression, NRN1 represents a promising candidate for novel diagnostic and therapeutic strategies in the evolving landscape of precision oncology." (PMID 41425077, 2025). "Their work demonstrated that NRN1 not only promoted human umbilical vein endothelial cell migration but also enhanced tumor-associated angiogenesis in vivo, supporting its contribution to pathological neovascularization." (PMID 41425077, 2025). "For further validation of the single NRN1 biomarker as a diagnostic tool, we recruited the proof-of-concept cohort from Hunan multicenter, including tumor (n = 156) and normal (n = 84)." (PMID 36765573, 2023). "We conclude that it is worth to pursue NRN1 as early tumor marker as the diagnostic procedure of determining the NRN1 serum level is inexpensive and readily performed." (PMID 27901477, 2017). "Furthermore, the categorization of secreted NRN1 in patient sera led to the assumption that NRN1 serum levels are obviously rather associated with early tumor stage than late stages." (PMID 27901477, 2017). "Significantly, blockade of NRN1 with specific monoclonal antibodies disrupted this immunosuppressive axis, restoring anti-tumor immunity." (PMID 41425077, 2025). "Since constitutive STAT3 activation is a well-established driver of tumor progression in various cancers, these findings position NRN1 as a potential upstream regulator of this oncogenic pathway." (PMID 41425077, 2025). "The increased expansion of CD45.1+ responder cells and reduced tumor growth further confirmed the reduced suppressive capacity of Nrn1-/- Treg cells." (PMID 39565188, 2024). "To evaluate Nrn1 expression under pathological tolerant conditions, we evaluated Nrn1 expression in T cells within the tumor microenvironment." (PMID 39565188, 2024). "Firstly, we used 32 previously collected frozen tumor tissues and 10 control tissues to detect the relative expression of NRN1 using RT-qPCR." (PMID 36765573, 2023). "We determined that 21 of 100 tumor tissues exhibited high NRN1 IHC staining in the cytoplasm of cancer cells." (PMID 34804954, 2021). "To assess the clinical significance of NRN1 in RCC, we performed immunohistochemical (IHC) analysis of NRN1 in ccRCC tumor samples obtained from distinct patients." (PMID 34804954, 2021). "A subsequent study further confirmed NRN1’s role in vascular remodeling and tumor biology." (PMID 41425077, 2025). "In addition to its effects on tumor cell intrinsic pathways, NRN1 appears to modulate the tumor microenvironment by enhancing immune evasion mechanisms." (PMID 41425077, 2025). "Furthermore, consistent with its known roles in neurovascular development, NRN1 exerts potent pro-angiogenic effects within the tumor microenvironment." (PMID 41425077, 2025). "When combined with immune checkpoint inhibitors such as anti-PD-1 antibodies, NRN1-targeted therapy produced synergistic anti-tumor effects, suggesting that NRN1 inhibition could enhance the efficacy of existing immunotherapies." (PMID 41425077, 2025). "NRN1 could enhance personalized immunomodulatory treatment regimens, as a positive regulator of checkpoint inhibitors to maximize the immune system’s tumor destruction." (PMID 41425077, 2025). "The potential of the STAT3 signaling pathway to act in both a tumor suppressive and oncogenic manner led us to investigate specific downstream targets – namely Vegf A, Mdr1, cMet - which were found to be upregulated under oncogenic levels of NRN1." (PMID 38705997, 2024). "Nrn1 mRNA level was significantly increased among tumor-associated Treg cells and non-Treg CD4 cells compared to cells from peripheral blood." (PMID 39565188, 2024). "Moreover, the number of CD45.1+ cells in tumor-draining lymph nodes and spleens increased significantly in Nrn1-/- Treg hosts compared to the ctrl group." (PMID 39565188, 2024).
tumor (continued). "PDC/PDCX-based and pathological analyses of RCC uncovered that NRN1 and its co-expressing molecule CXCR4 are positively associated with RCC patient prognosis and their silencing substantially suppresses PDC viability and PDCX tumor growth." (PMID 34804954, 2021). "Our data suggest that NRN1 exhibits a tumor-promoting effect in RCC in collaboration with CXCR4." (PMID 34804954, 2021). "The second most down-regulated gene was neuritin 1 (NRN1), which has been proposed as hypoxic marker and potential marker for tumor angiogenesis, followed by the proline-rich nuclear receptor coactivator 2 (PNRC2), syntaxin 19, and early growth response 1 (EGR1)." (PMID 28402269, 2017). "Therefore, we started to analyze serum-NRN1 in an ELISA system to proof its tumor marker capability." (PMID 27901477, 2017). "Consequently, strategies targeting NRN1 could simultaneously impair tumor angiogenesis and modulate immune responses, representing a promising dual-action therapeutic approach in highly vascularized and immunologically active tumors." (PMID 41425077, 2025). "Targeting NRN1 could offer a novel therapeutic approach to inhibit STAT3-driven tumor growth." (PMID 41425077, 2025). "There is recent evidence that NRN1 expression may be upregulated in different tumor entities." (PMID 38705997, 2024). "We further questioned whether NRN1-specific siRNAs can repress in vivo RCC tumor growth." (PMID 34804954, 2021). "While NRN1 is a glycosylphoshatidylinositol-anchored protein and involved in neuritogenesis, NRN1 expression is hypoxia-inducible and its high mRNA expression was observed in a restricted number of tumor cells around perinecrotic regions of a case of conventional RCC." (PMID 34804954, 2021). "In vivo studies using athymic nude mice demonstrated that xenografts overexpressing NRN1 exhibited markedly increased vascularization, as evidenced by elevated expression of the endothelial marker CD31 within tumor tissue." (PMID 41425077, 2025). "To evaluate the functional implication of Nrn1-/- Treg suppression in disease settings, we challenged the Rag2-/- hosts with the poorly immunogenic B16F10 tumor." (PMID 39565188, 2024). "Consistently, the CD45.1+ responder cell proportion among tumor lymphocyte infiltrates (TILs) was also increased, accompanied by an increased proportion of IFNγ + cells among CD8 TILs from Nrn1-/- Treg hosts." (PMID 39565188, 2024). "In the case of RCC-PDC2, the original patient tumor contained a tissue portion of ccRCC cells with eosinophilic cytoplasm and high NRN1/CXCR4 IHC staining, which feature was recapitulated in the established PDC spheroid culture and its PDCX tumor." (PMID 34804954, 2021). "The expression of NRN1 in the tumor group was significantly lower than that of normal group, with p < 0.05." (PMID 36765573, 2023). "Notably, we found that cells in cluster four shows an increased expression of genes related to the hypoxia (e.g., HILPDA), tumor angiogenesis (e.g., VEGF and NRN1) and glycolytic (e.g., ENO2)." (PMID 34805184, 2021). "Another possibility was that the key gene NRN1 might be only involved in the initiation of the tumor, but not progression." (PMID 36765573, 2023). "Nrn1 expression in murine Treg cells and non-Treg CD4+ cells from tumor infiltrates were compared to the Treg cells and non-Treg CD4+ T cells isolated from peripheral blood." (PMID 39565188, 2024).
cancer (7 papers, 2016 to 2025). A tumor composed of atypical neoplastic, often pleomorphic cells that invade other tissues. "Future research targeting NRN1 in cancer therapeutics should further clarify its angiogenic properties while harnessing its immunomodulatory properties." (PMID 41425077, 2025). "NRN1 can be a potential diagnostic and therapeutic target in RCC as analyzed by preclinical patient-derived cancer models and clinicopathological studies." (PMID 34804954, 2021). "Future research should aim to delineate the full spectrum of NRN1’s molecular targets, optimize its potential as a biomarker, and develop targeted therapies that could be integrated into personalized cancer treatment regimens." (PMID 41425077, 2025). "The manuscripts also revealed a guidance function of a soluble and secreted form of NRN1 that could be of importance for cancer cells." (PMID 27901477, 2017). "The KEGG pathway “pathway in cancer regulation of migration”, and the gene ontology terms of “regulation of cell migration” and “blood vessel development” were enriched for the partner genes of NRN1." (PMID 26972162, 2016). "In the present study, based on our findings and previous literature, we aimed to characterize whether NRN1 contributes to RCC biology, particularly to cancer stemness in ccRCC." (PMID 34804954, 2021). "Volcano plot showed significantly upregulated transcripts of transmembrane 4 L6 family member 1 (TM4SF1), neuritin 1 (NRN1), MT2, mucin‐like protein 3 (MUCL3), complement component 4B (C4B) and insulin‐like growth factor‐binding protein 4 (IGFBP4) genes in treated KPC mice cancer cells." (PMID 38131168, 2023).
neurodegenerative disease (3 papers, 2015 to 2025). A disorder of the central nervous system characterized by gradual and progressive loss of neural tissue and neurologic function. "The current knowledge of NRN1’s complex mechanistic foundations provide crucial insights for therapeutic efficacy in neurodegenerative diseases." (PMID 41425077, 2025). "The comprehensive examination of NRN1’s molecular mechanisms, neuroprotective properties, and diverse physiological functions presented in this review converges on a compelling opportunity for therapeutic innovation in neurodegenerative diseases." (PMID 41425077, 2025). "Nrn1 is a potential therapeutic target for CNS neurodegenerative diseases." (PMID 25719245, 2015). "Among these genes of neurodegenerative diseases, we observed that the NAP1L5 expression was significantly positively correlated with NEUROD6 and NRN1, whereas correlated with negatively CD163, ITPKB, and AQP1." (PMID 36568274, 2022).
peripheral neuropathy (2 papers, 2024 to 2025). A disorder affecting the peripheral nervous system. "We investigated the protective effect of maltol on neuromodulators in peripheral neuropathy and observed that maltol significantly enhanced the downregulation of NGF and Nrn1 caused by HG and PA." (PMID 39338303, 2024). "The neuroregenerative potential of NRN1 has also been validated in models of peripheral neuropathy." (PMID 41425077, 2025).
Muscular Disorders (1 paper, 2022). "From twenty genes of “Cellular Development, Cellular Movement, Skeletal and Muscular Disorders”, six DEGs in the top network related to RSK1 KO (TTLL12, ADMA22, FN1, LPAR1, MMP16, and NRN1) were highly correlated with RSK1 expression, with significant R and p values." (PMID 36684450, 2022).
NRN1 also shares sentences with these, for which no sentence is quoted: bipolar disorder (2 papers); gastric cancer (2); neurological disorders (2); benign tumors (1); cervical cancer (1); clear cell carcinoma (1); Clear Cell Renal Cell Carcinoma (1); cognitive decline (1); dementia (1); diabetic nephropathy (1); experimental autoimmune encephalomyelitis (1); Kaposi's sarcoma (1); megalencephalic leukoencephalopathy with subcortical cysts (1); membranous glomerulonephropathy (1); metastatic melanoma (1); multiple sclerosis (1); nephrosclerosis (1); Obesity (1); renal diseases (1); renal papillary cell carcinoma (1); septic shock (1); tauopathy (1); trauma (1); Urothelial Bladder Carcinoma (1).